CYP7B1 (cytochrome P450 family 7 subfamily B member 1)
Diseases named in the same sentence as CYP7B1 in open-access papers (continued):
Sharing a sentence is not in itself a finding about the gene and the disease.
leukemia (1 paper, 2022). A malignant (clonal) hematologic disorder, involving hematopoietic stem cells and characterized by the presence of primitive or atypical myeloid or lymphoid cells in the bone marrow and the blood. "Collectively, pharmacological inhibition of CYP7B1 (expected to have an elevation of 27HC) would potentially have fewer long-term hematological side effects, particularly when used in combination with chemotherapy or radiation for the treatment of leukemia patients." (PMID 36316327, 2022).
liver cancer (1 paper, 2017). An epithelial or non-epithelial malignant neoplasm that arises from the liver. "Therefore, the observed sex difference in FXR, BSEP, NTCP, CYP7A1 and CYP7B1 gene expressions may result in changes in enterohepatic circulation/BA synthesis and the differential accumulation of cytotoxic BAs in hepatocytes, thus contributing to a higher liver cancer incidence in male mice." (PMID 28345673, 2017).
lung carcinoma (1 paper, 2018). "To evaluate possible actions of 27HC in lung cancer pathogenesis, we determined the expression levels of CYP27A1, CYP7B1, ERα, and ERβ in a variety of lung cancer and normal lung cell lines." (PMID 30190703, 2018).
melanoma (1 paper, 2016). A malignant, usually aggressive tumor composed of atypical, neoplastic melanocytes. "Thus, genes controlling the turnover of vitamin D (CYP27B1, CYP24A1), vitamin A (ALDH1A3, AKR1B10), and cholesterol (CYP7B1), were up-regulated in psoriasis, whereas melanomas showed downregulation of genes regulating turnover of vitamin A (AKR1C3), and cholesterol (CYP39A1)." (PMID 26901218, 2016).
multiple sclerosis (1 paper, 2025). A progressive autoimmune disorder affecting the central nervous system resulting in demyelination. "Modulation of EBI2 signalling and/or local concentrations of CH25H, CYP7B1 and HSD3B7 in the brain and the brain blood vessels might result in disease-modulatory effects with potential therapeutic applications in the treatment of neuroinflammatory diseases including multiple sclerosis." (PMID 39999050, 2025).
ovarian failure (1 paper, 2017). "In female mice CYP7B1 knockout results in early onset puberty and ovarian failure." (PMID 28133578, 2017).
Parkinson ́s Disease (1 paper, 2024). "Single nucleotide polymorphisms (SNPs) with statistically significant association (p-value <0.05) to Parkinson ́s Disease (PD) for the genes of the four human cholesterol degrading cytochrome P450, CYP7B1, CYP27A1, CYP39A1 and CYP46A1." (PMID 39403150, 2024).
pregnancy disorder (1 paper, 2021). A disorder that is related to pregnancy. "The significant underexpression of ALOX15 (log2FC= −3.30) in mf-FGR placentas, accompanied by dysregulation of CYP7B1 (log2FC= −2.71) and other genes involved in inflammation, additionally underlines the role of immune response pathways in this pregnancy disorder." (PMID 33923632, 2021).
rectum adenocarcinoma (1 paper, 2025). An adenocarcinoma arising from the rectum. "CYP7B1 was a negative prognostic factor for ACC, while GPC3 correlated with unfavorable prognosis of UVM and rectum adenocarcinoma (READ)." (PMID 40433364, 2025).
rheumatoid arthritis (1 paper, 2015). A chronic, systemic autoimmune disorder characterized by inflammation in the synovial membranes and articular surfaces. "Upregulation of Cyp7B1 was observed in inflamed joints in collagen-induced arthritis model, a mouse model of rheumatoid arthritis (RA)." (PMID 25852561, 2015).
tumor (18 papers, 2015 to 2024). "Tumor CYP27A1 protein expression was associated with lower circulating HDL concentrations, while tumor CYP7B1 was associated with lower triglycerides." (PMID 32075687, 2020). "Even when age, tumor size, nodal status, and perioperative therapy are taken into consideration, low expression of CYP7B1 continues to be associated with poor overall outcome." (PMID 30190703, 2018). "In PTC, CYP7B1 was downregulated in aggressive tumor tissue, including PTC and ATC, compared to benign tumors, causing a high concentration of 27-hydroxycholesterol." (PMID 39000236, 2024). "High cholesterol diet mainly promoted colonization of tumor cells in lung tissue, which was restrained by Cyp27A1 knockdown and strengthened by Cyp7B1 knockdown, consistent with Hematoxylin and Eosin (HE) staining." (PMID 35379924, 2022). "We investigated CYP27A1 and CYP7B1 protein expression in the tumor as markers indicative of local 27HC metabolism." (PMID 32075687, 2020). "In premenopausal women, tumor CYP27A1 protein expression was associated with higher circulating DHEAS concentrations, and in perimenopausal women, tumor CYP7B1 was associated with lower testosterone." (PMID 32075687, 2020). "of the Cancer Genome Atlas found that CYP27A1 expression was similar in normal breast and ER + tumours but CYP7B1 expression was decreased by 50% in ER + tumours compared with normal breast tissue." (PMID 29421651, 2018). "That research highlighted the important roles played by the oxysterol metabolite 27-hydroxycholesterol which results from both anabolism and catabolism of CYP27A1 and CYP7B1 enzymes respectively in tumour pathophysiology." (PMID 27341022, 2016). "CYP7B1, the key enzyme responsible for the catabolism of 27‐HC, is associated with increased recurrence‐free survival, whereas the expression of the 27‐HC synthesising enzyme CYP27A1 is linked to unfavourable tumour characteristics." (PMID 37614064, 2023). "Differences in tumor characteristics by CYP7B1 and ERβ expression were minimal." (PMID 32075687, 2020). "Interestingly, in the case of TNBC, CYP27A1 expression is significantly upregulated in tumor samples compared to normal breast tissues, while CYP7B1 expression remains the same, suggesting a different regulatory mechanism in TNBC compared to ER-positive breast cancer." (PMID 32650428, 2020). "The expressions of each of the variables, namely, G9a nuclear, G9a cytoplasmic, G9a total, CYP7B1 and CYP27A1, were also analysed with regard to tumour grade and menopausal status using the median test." (PMID 37614064, 2023). "Further, abrogation of Cyp7B1, which catalyzes the conversion of 27-OHC to 7α, 27-di-OHC resulting in 27-OHC accumulation in plasma and tumor tissues, accelerates tumor growth in a mouse estrogen receptor-positive mammary adenocarcinoma model." (PMID 30283400, 2018). "CYP7B1, CYP8B1, CYP39A1, CYP46A1 and CYP51A1 each displayed a statistically significant relationship with location of tumour in the colon versus the rectum." (PMID 27341022, 2016). "Statistically significant expression changes were not noted in CYP7B1 and CYP27A1 between menopausal status and tumour grade." (PMID 37614064, 2023). "The distribution of positive/negative status for the tumor markers was comparable with distributions of ERβ, CYP27A1, and CYP7B1 previously reported." (PMID 32075687, 2020).
cancer (8 papers, 2015 to 2024). A tumor composed of atypical neoplastic, often pleomorphic cells that invade other tissues. "Messenger RNAs encoded by CYP7B1 and CYP27A1 were detected in all cancer grades; expression of CYP7B1 was significantly lower in poorly differentiated cancers compared to moderately differentiated cancers (P < 0.05)." (PMID 29371332, 2018). "CYP7B1 is primarily expressed in the liver and is involved in the metabolism of steroid hormones, playing a critical role in regulating the cell cycle, as well as the proliferative, invasive, and migratory activity of cancer cells." (PMID 38731981, 2024). "In a subgroup analysis of non-diabetic patients, elevated CYP7B1 expression was associated with an increased risk of biochemical recurrence, suggesting increased cancer aggressiveness." (PMID 38731981, 2024). "However, a slight increase in CYP7B1 expression was found in patients with luminal type A cancer, CYP7B1 is an enzyme inducer of 27-HC catabolism." (PMID 34093831, 2021). "In addition, the LXR/RXR signaling pathway and Cyp7B1, the enzyme responsible for the degradation of 27OHC, are significantly increased in women with luminal A cancer compared to those with TNBC cancer." (PMID 32079340, 2020). "As concentrations of CYP7B1 mRNAs were significantly decreased in poorly compared to moderately differentiated cancers and expression of CYP27A1 did not change significantly across EC grades; we believe this would favour increased bioavailability of 27HC with increasing grade." (PMID 29371332, 2018).
infection (8 papers, 2015 to 2025). The state of being infected such as from the introduction of a foreign agent such as serum, vaccine, antigenic substance or organism. "Hence, CYP7B1 represents an appealing candidate as a modifier of infection susceptibility due to its contribution to the synthesis of virions and the initiation of antiviral defense." (PMID 26399852, 2015). "Following infection with M. tuberculosis, mice with diet-induced dysglycemia had reduced lung expression of Cyp7b1 and Gpr183, accompanied by impairment in macrophage migration to the lungs and reduced control of infection." (PMID 38693938, 2024). "Similar results were obtained in primary murine hepatocytes after Ad-378 infection or Ant-378 transfection, suggesting that miR-378 regulates hepatic CYP7B1, CYP8B1, and CYP27A1 expression in a cell-autonomous manner." (PMID 33754066, 2021). "We thus determined whether infection with the S. Typhimurium wild type decreased expression of genes involved in bile acid synthesis, including Cyp7a1, Cyp8b1, Cyp27a1, and Cyp7b1." (PMID 40938708, 2025). "Similarly, the activation of genes such as Serping1, Sparc, Pcsk5, Fgf7, and Cyp7b1 indicated the temporal activation of cell migration and immune suppression during infection." (PMID 38767331, 2024). "However, unexpectedly, infection with adenovirus encoding CYP7B1 did not induce significant changes in pro-inflammatory factor expression." (PMID 38036731, 2023). "In contrast, the mRNA and protein levels of hepatic CYP7B1, CYP8B1, and CYP27A1 were all increased by Ad-378 infection and decreased by Ant-378 administration, respectively." (PMID 33754066, 2021). "Notably, Cyp7b1 does not significantly increase upon infection, suggesting that Ch25h induction in macrophages is rate-limiting for production of chemotactic oxysterols in the lung." (PMID 40766699, 2025). "Since synthetic agomir for miR-378* (AgomiR-378*) transfection could not affect the mRNA expression of CYP7B1, CYP8B1, and CYP27A1, we speculated that miR-378 but not miR-378* contributes to the effect of Ad-378 infection on the expression of these enzymes." (PMID 33754066, 2021).
neurodegenerative disease (4 papers, 2017 to 2025). A disorder of the central nervous system characterized by gradual and progressive loss of neural tissue and neurologic function. "The mutation in the CYP7B1 gene, responsible for 25-OHC metabolism, caused the hereditary degenerative disease involving motor neurons." (PMID 28060747, 2017). "Modulation of the levels of CH25H, CYP7B1 and HSD3B7 enzymes directly in the brain may thus be another way to limit the increased chemotaxis or entry of EBI2-expressing encephalitogenic immune cells into the CNS during acute inflammation, neuroinflammatory disease or neurodegenerative diseases." (PMID 39999050, 2025).
cardiovascular disorder (1 paper, 2021). A disease involving the cardiovascular system. "Although there is no any studies focusing on the association of CYP7B1 polymorphisms with cardiovascular disorders risk, we carried out the FPRP analysis to detect whether the positive findings in our study were just chance or noteworthy observations." (PMID 34493281, 2021).
liver (1 paper, 2015). "Furthermore, the upregulation of bile acid synthetic enzymes CYP7B1 and CYP8B1 may be attributed, at least in part, to FXR reduction, which is associated with increased expression of their suppressors HNF4α and LRH-1 in human obstructive cholestatic liver." (PMID 25798860, 2015).
neurological disorders (1 paper, 2023). "Impaired cholesterol homeostasis in the CNS contributes to neurological disorders such as CTX and SPG5, which are caused by biallelic mutations in the CYP27A1 and CYP7B1 genes, respectively." (PMID 37024986, 2023).
CYP7B1 also shares sentences with these, for which no sentence is quoted: fibrosis (2 papers); Spastic paraparesis (2); Aagenaes syndrome (1); Alagille syndrome (1); Ataxia (1); benign thyroid tumors (1); benign tumors (1); Cerebellar atrophy (1); Cognitive impairment (1); congenital bile acid synthesis defect 3 (1); coronary heart disease (1); dementia (1); Dubin-Johnson syndrome (1); gallbladder cancer (1); holoprosencephaly (1); Hyperglycemia (1); hyperlipidemia (1); Knee Osteoarthritis (1); lymph node metastasis (1); malignant neoplasms of the prostate (1); Metabolism (1); non-alcoholic fatty liver disease (1); non-alcoholic steatohepatitis (1); Nystagmus (1); Prediabetes (1); primary immunodeficiency (1); psoriasis (1); rheumatic disease (1); schizophrenia (1); ulcerative colitis (1).
A further 2 diseases each share a sentence with CYP7B1 in 1 paper.